MR1 (major histocompatibility complex, class I-related)
Description:
Antigen-presenting molecule specialized in displaying microbial pyrimidine-based metabolites to alpha-beta T cell receptors (TCR) on innate-type mucosal-associated invariant T (MAIT) cells. In complex with B2M preferentially presents riboflavin-derived metabolites to semi-invariant TRAV1.2 TCRs on MAIT cells, guiding immune surveillance of the microbial metabolome at mucosal epithelial barriers. Signature pyrimidine-based microbial antigens are generated via non-enzymatic condensation of metabolite intermediates of the riboflavin pathway with by-products arising from other metabolic pathways such as glycolysis. Typical potent antigenic metabolites are 5-(2-oxoethylideneamino)-6-D-ribitylaminouracil (5-OE-RU) and 5-(2-oxopropylideneamino)-6-D-ribitylaminouracil (5-OP-RU), products of condensation of 5-amino-6-D-ribityaminouracil (5-A-RU) with glyoxal or methylglyoxal by-products, respectively. May present microbial antigens to various TRAV1-2-negative MAIT cell subsets, providing for unique recognition of diverse microbes, including pathogens that do not synthesize riboflavin. Upon antigen recognition, elicits rapid innate-type MAIT cell activation to eliminate pathogenic microbes by directly killing infected cells. During T cell development, drives thymic selection and post-thymic terminal differentiation of MAIT cells in a process dependent on commensal microflora (By similarity). Acts as an immune sensor of cancer cell metabolome. May present a tumor-specific or -associated metabolite essential for cancer cell survival to a 'pan-cancer' TCR consisting of TRAV38.2-DV8*TRAJ31 alpha chain paired with a TRBV25.1*TRBJ2.3 beta chain on a non-MAIT CD8-positive T cell clone (MC.7.G5), triggering T cell-mediated killing of a wide range of cancer cell types. Allele MR1*01: Presents microbial-derived metabolite 5-OP-RU to semi-invariant TRAV1.2-TRAJ33-TRBV6.1 (A-F7) TCR on MAIT cells. Presents nucleobase carbonyl adducts generated during oxidative stress. Captures M3Ade, a nucleobase adduct composed of one adenine modified by a malondialdehyde trimer, for recognition by MR1-restricted T cell clones expressing a polyclonal TCR repertoire. Displays moderate binding affinity toward tumor-enriched pyridoxal and pyridoxal 5'-phosphate antigens. Allele MR1*04: Presents tumor-enriched metabolite pyridoxal to pan-cancer 7.G5 TCR on T cells enabling preferential recognition of cancer cells. May act as an alloantigen.
Synonyms: HLALS
Tractability: Small molecule: a structure with a bound ligand is known. Antibody: UniProt places it where antibodies can reach, with high confidence; its Gene Ontology location is reachable by antibodies, with high confidence; UniProt predicts a signal peptide or a membrane-spanning region; the Human Protein Atlas places it where antibodies can reach. PROTAC: ubiquitination databases record sites on it.
Gene: Protein-coding gene on chromosome 1 (181,033,374 to 181,061,938, forward strand). Ensembl gene ENSG00000153029.
Subcellular location: Cell membrane; Endoplasmic reticulum membrane; Golgi apparatus membrane; Early endosome membrane; Late endosome membrane; Cell membrane (Isoform 1); Cell membrane (Isoform 3); Secreted (Isoform 4)
Subcellular location (Human Protein Atlas): Plasma membrane
Gene Ontology:
Molecular function: beta-2-microglobulin binding; protein binding; T cell receptor binding; MHC class I receptor activity
Biological process: antigen processing and presentation of exogenous antigen; defense response to Gram-negative bacterium; defense response to Gram-positive bacterium; positive regulation of T cell mediated cytotoxicity directed against tumor cell target; immune response; T cell differentiation in thymus; regulation of T cell mediated immunity
Cellular component: early endosome membrane; endoplasmic reticulum; endoplasmic reticulum membrane; Golgi membrane; late endosome membrane; plasma membrane; external side of plasma membrane; extracellular region
Genetic constraint (gnomAD): Loss-of-function variants: 40 observed, 37.66 expected, observed/expected ratio (o/e) 1.06, 90% interval 0.82 to 1.38. The upper end of that interval is the gene's LOEUF score, 1.38, which puts it in group 5 of 6, group 1 being the genes least tolerant of losing a copy. Missense variants: 373 observed, 428.32 expected, observed/expected ratio (o/e) 0.87, 90% interval 0.8 to 0.95. Synonymous variants: 149 observed, 159.26 expected, observed/expected ratio (o/e) 0.94, 90% interval 0.82 to 1.07.
Homologues: Orthologues: chimpanzee MR1 (99% identical), macaque MR1 (91% identical), guinea pig MR1 (77% identical), mouse Mr1 (76% identical), pig MR1 (75% identical), rat Mr1 (75% identical). Paralogues in human: HLA-C (37% identical), HLA-B (37% identical), HLA-E (36% identical), HLA-F (36% identical), HLA-A (36% identical), HLA-G (36% identical), HFE (33% identical), AZGP1 (29% identical), FCGRT (25% identical), MICA (24% identical), MICB (24% identical), CD1A (22% identical), and 10 more.
Diseases named in the same sentence as MR1 in open-access papers:
MR1 is named in the same sentence as 126 diseases in open-access papers, as found by Europe PMC text mining. Sharing a sentence is not in itself a finding about the gene and the disease. The quoted sentences say what the papers report.
viral infections (21 papers, 2010 to 2025). "Mucosal-associated invariant T (MAIT) cells are restricted by MR1 and are known to protect against bacterial and viral infections." (PMID 36189274, 2022). "MAIT cells are activated by viral infections in an MR1-independent manner through innate cytokines and TCR receptors." (PMID 38550591, 2024). "HCMV infection also inhibited E.coli driven MAIT cell activation consistent with efficient targeting of MR1 surface expression by viral infection." (PMID 36845106, 2023). "HCMV infection of parental cells also inhibited E.coli driven MAIT cell activation in parental cells consistent with efficient targeting of MR1 surface expression by viral infection." (PMID 36845106, 2023). "MR1-independent responses are likely important in MAIT cell responses to viral infections and in diseases driven by cytokine storms provoked by bacterial exotoxins." (PMID 37654490, 2023). "This study builds upon our previous reports identifying that suppression of MR1 by viral infection is a feature of herpesvirus infection." (PMID 36845106, 2023). "The suppression of Mr1 by viral infection has been shown to inhibit bacterial driven MAIT TCR-activation." (PMID 36417363, 2022). "A recent study suggested that viral infection downregulates surface expression of MR1 and thereby presentation of MR1-bound antigen to MAIT cells, through the HSV-1 protein US344." (PMID 32963314, 2020). "Vitamin B2 metabolites presented by MR1 are the classical activating ligand of MAIT cells, but they can also be activated in an MR1-independent and/or cytokine-driven manner in response to viral infection." (PMID 32560123, 2020). "Cytokines, such as IL-12, IL-18, and type I IFN, released by APCs upon bacterial or viral infection can also activate MAIT cells in a MR1-independent manner." (PMID 32788367, 2020). "One possible function is protection of the fetus against bacterial and fungal infections, but also against viral infections since MAIT cells are also activated by inflammatory signals in an MR1-independent manner." (PMID 31244846, 2019). "Third, MAIT cells constitutively express or acquire cytolytic effector molecules, including perforin (PFN), granzymes (GZMs) and granulysin, during viral infections, which can be deployed to eliminate MR1+ target cells and extracellular bacteria encountered during secondary infections." (PMID 37384813, 2023). "Given that MAIT cell numbers and function are altered in human cohorts including bacterial infection or sepsis, viral infection and autoimmune disease, it remains to be shown whether there is a direct link to MR1 expression." (PMID 32973800, 2020). "We hypothesize that secondary non-viral infections may enhance the severity of COVID-19 by activating MR1-dependent MAIT cells." (PMID 32849648, 2020). "Additionally, MAIT cells sense and respond to viral infections in an MR1-independent fashion." (PMID 37384813, 2023). "Thus, we suggest that activation of MAIT cells in secondary non-viral infection via the MR1-dependent pathway may be a factor that enhances the progression of COVID-19, and IL-17 production may be one of the mediators." (PMID 32849648, 2020). "In the context of viral infections, MAIT cells have been shown to be host protective via cytokine-driven, MR1-independent mechanisms." (PMID 38950078, 2024). "Downregulation of MR1 by HSV-1 and CMV suggests that TCR-dependent MAIT cell activation may also be impaired in the context of viral infection." (PMID 32973800, 2020). "In addition to viral infections, MAIT cells also respond to infections with some bacterial species, such as Mycobacterium tuberculosis, Mycobacterium bovis bacillus Calmette–Guérin, and Enterococcus faecalis, in an MR1-independent manner." (PMID 29176983, 2017). "The best characterized role of MAIT cells to date in responding to viral infection is through virus induced, cytokine mediated activation of MAIT cells, independent of the MR1:TCR axis." (PMID 36845106, 2023).
viral infections (continued). "Upon cytokine-mediated activation in viral infections, MAIT cells can produce IFN-γ and GzmB, which can be suppressed or even abrogated by anti-IL-18 but not by MR1-blocking." (PMID 29176983, 2017). "However, recent studies have shown that not only in viral diseases, but also in some non-infectious diseases, MAIT cells can be activated in an MR1-independent manner." (PMID 29176983, 2017).
melanoma (15 papers, 2017 to 2025). A malignant, usually aggressive tumor composed of atypical, neoplastic melanocytes. "To exclude the contribution of molecules other than MR1 to this reactivity, we established a new assay using beads coated with soluble MR1, produced by the melanoma cell line A375, as stimulatory reagents." (PMID 40040716, 2025). "These experiments show that it is possible to culture T cells that recognize a WT melanoma cell line via the MR1 molecule from all donors tested." (PMID 39744940, 2025). "These primed T cells were then enriched following exposure to WT melanoma line MM909.24 or MR1-KO MM909.24 overexpressing MR1*01 and expanded for 2 weeks prior to testing." (PMID 39744940, 2025). "Two of the lines enriched with MM909.24 overexpressing MR1*01 responded well to these targets but exhibited dependency on overexpressed MR1*01 for maximal reactivity, with minimal activation toward WT melanoma cells." (PMID 39744940, 2025). "Of all the MHC complexes examined for brain and skeletal metastases, we determined that there is an organ specific expression of mhc1uba (human ortholog, MR1) for both the melanoma cells and the resident and infiltrating immune cells." (PMID 38313277, 2023). "A previous study on B16F10 melanoma suggested that MAIT cells induce tumor development in a manner that is dependent on MR1 and agonists, such as 5-OP-RU." (PMID 35379387, 2022). "B6-MAITcast MR1−/− mice, which lack MAIT cells, were significantly protected in an experimental metastasis model involving intravenous inoculation of B16F10 melanoma cells, relative to B6-MAITcast MR1 WT mice." (PMID 34362900, 2021). "5-OP-RU pulsing significantly upregulated MR1 on B16F10 melanoma cells, suggesting the tumor cells were able to present the 5-OP-RU antigen on their surface in an MR1-dependent manner." (PMID 34362900, 2021). "Incorporation of MR1-recognizing TCR into patients-derived T-cells resulted in efficient destruction of melanoma cells by recombinant MR1 TCR T-cells." (PMID 32973401, 2020). "MR1T cells (clone DGB129) can recognize human leukemia (CCRF-SB and THP1) and melanoma (A375-MR1) cancer cell lines through MR1 presentation in vitro." (PMID 33185693, 2020). "We also tested activated B cells as target cells, as they may have increased levels of MR1 expression, alongside melanoma FM72." (PMID 39744940, 2025). "Characterization of MR1-restricted melanoma reactive T cells." (PMID 39744940, 2025). "In a distinct model involving subcutaneous growth of low dose B16F10 melanoma cells, we again found that tumor growth was significantly inhibited in B6-MAITcast MR1−/− mice relative to B6-MAITcast MR1 WT mice, leading to enhanced survival of MAIT cell-deficient mice." (PMID 34362900, 2021). "After the initial priming, 2 of 3 donors had T cells reactive toward overexpressed MR1 on either C1R or melanoma cells, but no MR1-restricted reactivity with WT melanoma cells." (PMID 39744940, 2025). "Additionally, the TCR-KI T cells released granzyme B when incubated with melanoma FM72, which is a very good target of the MC.7.G5 TCR and MR1*01 homozygous, but also at very reduced levels of activation compared with the TCR-replaced T cells." (PMID 39744940, 2025). "In addition, Mr1−/− mice injected with B16F10 melanoma cells show reduced metastasis compared to wild type mice, reversed by adoptive transfer of MAIT cells into Mr1−/− mice." (PMID 40422223, 2025). "MR1 knockout mice (therefore without MAIT cells) are resistant to metastasis of inoculated B16F10 melanoma, which is dependent on NK cells." (PMID 36551916, 2022). "This T cell clone (DGB129) recognized cell lines constitutively displaying surface MR1 (CCRF-SB lymphoblastic leukemia cells, or THP-1 monocytic leukemia cells) or A375 melanoma cells (A375-MR1) transfected with an MR1-β2m fusion gene construct in the absence of any exogenously added antigens." (PMID 28518056, 2017).
melanoma (continued). "Notably, pre-pulsing B16F10 melanoma cells with 5-OP-RU enhances MAIT cell-mediated tumor control, partly through modulation of NK cell responses, although, in a different context, MR1-expressing B16F10 cells can suppress NK cell frequency via MAIT activation." (PMID 40746558, 2025).
lung carcinoma (11 papers, 2016 to 2025). "Based on that the level of MR‐1 mRNA was highly expressed in lung cancer, we attempted to explore the protein expression pattern of MR‐1 in lung cancer by HPA." (PMID 38342606, 2024). "The results showed that MR‐1 is highly expressed in protein level of lung cancer compared to normal lung tissue." (PMID 38342606, 2024). "The study is the first to report the promoting effect of MR‐1 on the development and metastasis of non‐small cell lung cancer (NSCLC)." (PMID 38342606, 2024). "In a model of lung cancer, mice that lack the MR1 locus or in which MR1 is blocked by antibody show decreased tumor growth and reduced metastasis." (PMID 33969420, 2021). "Another MR1-T cell (clone MC.7.G5) was identified in HLA-mismatched healthy donor cells co-cultured with A549 lung cancer cells, and its MR1 target was confirmed using CRISPR-Cas9 lentivirus libraries." (PMID 33185693, 2020). "We generated isogenic MR1−/− clonal derivatives of the A549 lung carcinoma and THP-1 monocytic cell lines and used these to study T cell responses to intracellular pathogens." (PMID 27307560, 2016). "In summary, the interruption of MR‐1/ITCH/ NICD3/HES1 axis may be a new strategy for lung cancer treatment." (PMID 38342606, 2024). "The MR‐1/ITCH/NICD3/HES1 axis may be a promising therapeutic target in the progression of lung cancer." (PMID 38342606, 2024). "To investigate whether MR‐1 regulates the metastasis of lung cancer cells, we profiled RNA sequencing (RNA seq) analysis to identify different gene expression patterns in control and MR‐1‐knockdown H1299 cells." (PMID 38342606, 2024). "In breast, renal, thyroid, and lung cancer, as well as glioma, MR1 gene expression is increased." (PMID 36944969, 2023). "Prior researchers have observed MR1 gene expression by a variety of different cell types, including neoplastic cells of epithelial origin, such as HeLa cells (cervical carcinoma) and A549 (lung carcinoma)." (PMID 30208917, 2018). "Then we plan to explore the effect of TMP22 on the process of MR‐1‐mediated the regulation of NICD3 and lung cancer metastasis." (PMID 38342606, 2024). "Disrupting the interaction between MR‐1 and NICD3 effectively inhibits the metastasis of lung cancer cells and accelerates the degradation of NICD3 by ITCH." (PMID 38342606, 2024). "MC.27.759S and MC.7.G5 both killed A549 WT (MR1*01/*04) lung cancer cells but failed to kill these cells when MR1 was knocked out using CRISPR technology." (PMID 39744940, 2025). "In summary, interference with the interaction between MR‐1 and NICD3 in the progression of lung cancer may be a promising therapeutic target." (PMID 38342606, 2024). "Our study suggests that MR‐1 increases the production of NICD3 in the cytoplasm, leading to increasing NICD3 into the nucleus, exerting the transcriptional activation, and promoting the metastasis of lung cancer cells." (PMID 38342606, 2024). "A study employing an in vivo lung cancer mouse model determined that tumor initiation, growth, and metastasis were significantly reduced for MR1 knockout mice, suggesting that MAIT cells promote tumor progression in a TCR-MR1-dependent manner." (PMID 36463401, 2023). "Lung cancer has a significantly lower expression of MR1 compared to normal lung tissue (P = .0025)." (PMID 33948562, 2021).